WNT5A (Wnt family member 5A)
Diseases named in the same sentence as WNT5A in open-access papers (continued):
Sharing a sentence is not in itself a finding about the gene and the disease.
cardiac disease (4 papers, 2019 to 2025). "BMI, SFRP5, WNT5a, and JAK have been confirmed to be independent predictors of cardiac disease, highlighting their potential as biomarkers for risk stratification." (PMID 41465371, 2025). "Our assumption is based on previous findings that WNT-5a was found to be elevated in patients with advanced heart disease." (PMID 36440011, 2022). "Clinically, inhibition of Prrx2 or Wnt5a is an effective approach to improve cardiac remodelling in patients with ischaemic heart diseases." (PMID 31880857, 2020). "This novel mechanism not only uncovers a molecular mechanism by which Wnt5a signalling is re‐activated in cardiac fibroblasts during ischaemia in vivo, but also provides a novel target for exploring new drugs to improve the prognosis of ischaemic heart disease." (PMID 31880857, 2020). "Multivariate analysis confirmed BMI, SFRP5, WNT5a, and JAK as independent predictors of cardiac disease, suggesting their potential as prognostic biomarkers." (PMID 41465371, 2025). "Univariate analysis identified high BMI, low SFRP5, elevated WNT5a and JAK, and reduced FS and EF as significant predictors of cardiac disease (p < 0.001)." (PMID 41465371, 2025).
metabolic disease (4 papers, 2018 to 2025). A congenital disorder (due to inherited enzyme abnormality) or acquired (due to failure of a metabolically important organ) disorder resulting from an abnormal metabolic process. "Abnormal Wnt5a expression, mitochondrial abnormalities and calcium overload have been detected in many metabolic diseases." (PMID 40008536, 2025). "Wnt family member 5A (WNT5A) is a novel mediator of inflammation in metabolic diseases and has been reported to be a typical ligand of noncanonical Wnt signaling." (PMID 35350980, 2022).
hematological malignancies (3 papers, 2013 to 2021). "Heightened co-expression and dysregulated signaling associated with Toll-like receptor 3 (TLR3) and Wnt5a is an integral component of solid tumors and hematological malignancies." (PMID 29371911, 2017).
neurological disorders (3 papers, 2014 to 2022). "Wnt5a was also involved in Human Immunodeficiency Virus (HIV) associated neurological disorders by promoting IL-1β, IL-6 and TNF-α production in the spinal cord." (PMID 24993819, 2014). "Furthermore, among these EMT genes, four genes (MMP2, MAP1B, SNAI2, and WNT5A) were involved in neurologic diseases." (PMID 36553576, 2022). "Interestingly, four EMT genes (MAP1B, SNAI2, MMP2, and WNT5A) were also involved in neurological diseases, brain metastasis, and response to platinum-based chemotherapy or tyrosine–kinase inhibitors." (PMID 36553576, 2022). "Interestingly, four EMT genes (MAP1B, SNAI2, MMP2, WNT5A) are also involved in neurological diseases, in brain metastasis, and interact with platinum-based chemotherapy and tyrosine–kinase inhibitors." (PMID 36553576, 2022).
brain disorder (2 papers, 2012 to 2022). A disease affecting the brain or part of the brain. "Although the role of WNT-5A for brain development has been mapped in some detail, less is known of its involvement in brain disorders in the adult." (PMID 22647544, 2012).
haematopoietic tumours (2 papers, 2010 to 2013). "The WNT5A gene was previously found silenced in colorectal and hematological cancers due to hypermethylation of a CpG island encompassing exon 1, the initiation site of the WNT5A-L isoform." (PMID 24260410, 2013). "As we show here for ROR2, WNT5A repression in colon and haematopoietic tumours is mediated by aberrant promoter hypermethylation." (PMID 20591152, 2010).
infectious disease (2 papers, 2013 to 2018). A disorder directly resulting from the presence and activity of a microbial, viral, or parasitic agent in humans. "Activated Wnt5a signaling has been implicated in the up-regulation of proinflammatory cytokines in autoimmune and infectious diseases." (PMID 23861788, 2013). "Further analysis of the magnitude and dynamics of Wnt5A signaling in different experimental contexts and in clinical infectious disease scenarios is thus essential." (PMID 29686674, 2018).
colon polyps (1 paper, 2024). "This is the first study analyzing the gene expression of APC, Wnt3A, Wnt5A, BCL9, and LEF1 in the colon polyps vs. adjacent mucosa and vs. normal mucosa from control individuals." (PMID 39200196, 2024).
WNT5A also shares sentences with these, for which no sentence is quoted: idiopathic pulmonary fibrosis (11 papers); breast (5); benign tumors (4); chronic periodontitis (3); lung squamous cell carcinoma (3); acute myeloid leukemia (2); Arrhythmia (2); autoimmune disease (2); bladder urothelial carcinoma (2); chronic hepatitis (2); Duchenne muscular dystrophy (2); end stage renal disease (2); gastrointestinal stromal tumor (2); hypospadias (2); interstitial lung disease (2); myocarditis (2); neurodegenerative disease (2); psoriatic arthritis (2); rectal adenocarcinoma (2); sarcoma (2); skeletal dysplasia (2); small cell lung carcinoma (2); systemic lupus erythematosus (2); thymoma (2); thyroid tumor (2); /T-cell lymphoma (1); acute leukemia (1); age-related macular degeneration (1); allergic rhinitis (1); Alport syndrome (1).
A further 98 diseases each share a sentence with WNT5A in 1 paper.